RPL21 (ribosomal protein L21)
Description:
Component of the large ribosomal subunit. The ribosome is a large ribonucleoprotein complex responsible for the synthesis of proteins in the cell.
Synonyms: L21; FLJ27458; MGC71252; MGC104274; MGC104275; DKFZp686C06101; eL21; HYPT12
Tractability: Small molecule: an approved drug acts on it; a structure with a bound ligand is known; a high-quality ligand is known. PROTAC: ubiquitination databases record sites on it; its protein half-life has been measured; a small molecule that binds it is known. Other modalities: a drug acting on it is in phase 2 or 3 trials.
Target class: Other cytosolic protein
Gene: Protein-coding gene on chromosome 13 (27,251,283 to 27,259,609, forward strand). Ensembl gene ENSG00000122026.
Subcellular location: Cytoplasm, cytosol; Cytoplasm; Endoplasmic reticulum
Subcellular location (Human Protein Atlas): Cytosol; Endoplasmic reticulum; Nucleoli fibrillar center
Pathways (Reactome):
Metabolism of proteins: Eukaryotic Translation Termination; Formation of a pool of free 40S subunits; GTP hydrolysis and joining of the 60S ribosomal subunit; L13a-mediated translational silencing of Ceruloplasmin expression; PELO:HBS1L and ABCE1 dissociate a ribosome on a non-stop mRNA; Peptide chain elongation; Ribosome Quality Control (RQC) complex extracts and degrades nascent peptide; SRP-dependent cotranslational protein targeting to membrane; ZNF598 and the Ribosome-associated Quality Trigger (RQT) complex dissociate a ribosome stalled on a no-go mRNA
Metabolism of RNA: Major pathway of rRNA processing in the nucleolus and cytosol; Nonsense Mediated Decay (NMD) enhanced by the Exon Junction Complex (EJC); Nonsense Mediated Decay (NMD) independent of the Exon Junction Complex (EJC)
Cellular responses to stimuli: Response of EIF2AK4 (GCN2) to amino acid deficiency
Developmental Biology: Regulation of expression of SLITs and ROBOs
Disease: Viral mRNA Translation
Metabolism: Selenocysteine synthesis
Gene Ontology:
Molecular function: protein binding; RNA binding; structural constituent of ribosome
Biological process: cytoplasmic translation; negative regulation of myoblast fusion; spermatogenesis; striated muscle contraction; translation
Cellular component: cytosol; cytosolic large ribosomal subunit; cytosolic ribosome; endoplasmic reticulum; fibrillar center; membrane; cytoplasm; ribosome
Homologues: Orthologues: chimpanzee RPL21 (100% identical), rabbit RPL21 (100% identical), tropical clawed frog rpl21 (89% identical), rat AABR07043626.1 (88% identical), zebrafish rpl21 (85% identical), Drosophila melanogaster RpL21 (72% identical), Caenorhabditis elegans rpl-21 (64% identical).
Diseases named in the same sentence as RPL21 in open-access papers:
RPL21 is named in the same sentence as 28 diseases in open-access papers, as found by Europe PMC text mining. Sharing a sentence is not in itself a finding about the gene and the disease. The quoted sentences say what the papers report.
pancreatic cancer (4 papers, 2020 to 2023). "RPL21 (ribosomal protein gene 21) has been found to be associated with the proliferation of pancreatic cancer cells and may be used as a potential marker for cervical intraepithelial neoplasia, but there are few reports in ovarian cancer." (PMID 36424614, 2022). "In its turn, RPL21 KD by siRNA inhibits cell proliferation and DNA replication as well as induces G1 cell cycle arrest in pancreatic cancer cells PANC-1 and Bxpc-3, in vitro and in vivo." (PMID 34873618, 2021). "Our previous study showed that the ribosomal protein L21 (RPL21) may play an important role in the development and survival of pancreatic cancer." (PMID 33014855, 2020). "Finally, we determined the effect of knock down of RPL21 on the growth of subcutaneously implanted pancreatic tumors in vivo." (PMID 33014855, 2020). "RPS8, RPL15 and RPL21 could also serve as biomarkers in pancreatic cancer." (PMID 34873618, 2021). "The present paper reported that, in pancreatic cancer (PC) cells, E2F1, CCND1, CCNE1, and all members of the MCM2-7 family were downregulated after inhibition of the RPL21 expression, leading to the reduction of DNA replication." (PMID 33014855, 2020).
breast carcinoma (2 papers, 2016 to 2024). "A classifier combining the expression signature of RPL39L, RPL26L1, and RPL21 has an even greater predictive power, comparable to that of genes that are most predictive for the relapse-free survival of breast cancer patients." (PMID 27884178, 2016). "In breast cancer datasets, the five most important mRNAs were GABARAP, PFDN5, RPL21, CFB, and PCED1A." (PMID 39495117, 2024).
head and neck squamous cell carcinoma (2 papers, 2023). A squamous cell carcinoma that arises from any of the following anatomic sites: lip and oral cavity, nasal cavity, paranasal sinuses, pharynx, larynx, and salivary glands. "Finally, to determine whether 5′UTR isoform switches could also play a role in human cancer, we assessed RPL21 and RPL29 levels in 519 human head and neck squamous cell carcinoma (HNSCC) patients." (PMID 36550360, 2023). "Notably, we found that the two 5′TOP motif-containing, but not the TOP-less, RPL21 transcript isoforms strongly correlated with overall survival in human head and neck squamous cell carcinoma patients." (PMID 36550360, 2023). "Notably, we found that the two TOP motif-containing, but not the TOP-less, RPL21 transcript isoforms strongly stratified overall survival in human head and neck squamous cell carcinoma patients and resulted in medium overall survival differences of up to 3.5 years." (PMID 36550360, 2023). "Notably, increased expression of TOP motif-containing, but not the TOP-less, RPL21 transcripts strongly correlated with shorter overall survival in head and neck squamous cell carcinomas (HNSCC), indicating that the precise configuration of the 5′UTR isoforms may be relevant for disease progression." (PMID 36550360, 2023).
prostate carcinoma (2 papers, 2019 to 2022). A carcinoma that arises from epithelial cells of the prostate gland. "Other ribosomal proteins have been reported in prostate cancer pathogenesis, such as RPL19, RPL21, and RPL24, and have been proposed as good prostate cancer biomarkers." (PMID 36140189, 2022). "The top 10 genes upregulated in TRAMP mice are TNFSF, RPL22, EIF4, SLC2A, LMO2/3, KRT, RPS21, RPS19, RPL21, and NEK of which all 10 were upregulated in human prostate cancer dataset." (PMID 30972102, 2019).
Age-related cataract (1 paper, 2024). A type of cataract (opacification of the lens) that forms during the course of aging. "Ribosomal protein L21 is a constitutive protein of the large ribosomal subunit, and found in the cytoplasm of human cells, participating in embryogenesis, odontogenesis, and the formation of age-related cataracts in humans." (PMID 38206477, 2024).
thyroid carcinomas (1 paper, 2016). "Among these, RPL26L1 and RPS27L were exclusively up-regulated in breast and thyroid carcinomas, respectively, whereas RPL21 had decreased expression in breast and uterine cancers." (PMID 27884178, 2016).
cancer (9 papers, 2011 to 2023). A tumor composed of atypical neoplastic, often pleomorphic cells that invade other tissues. "To explore the possible role of RPL21 in tumor progression, we investigated the RPL21 expression in various cancers from the Gene Set Cancer Analysis platform GSCA and observed a remarkable increase in its expression in CRC samples." (PMID 37062845, 2023). "Our findings suggest that siRNA against the RPL21 gene possesses a potential anti-cancer activity for PC cells by inhibiting their proliferation and DNA replication, as well as inducing cell cycle G1 arrest and cell apoptosis." (PMID 33014855, 2020). "Some of these proteins, including Rpl21, Atic, Eif3s2, Echs1, Eps15 and Ywhab, have previously been reported to be involved in cancer genesis and progression." (PMID 23895178, 2013). "Since RPL21 and RPL10A are highly expressed in cancer, we confirmed their upregulation in our model of tumorigenesis." (PMID 27551510, 2016). "RPL21 KD promotes apoptosis in these two types of cells but not in normal ones by increasing caspase 8 activity, suggesting that targeting RPL21 could be an effective anti-cancer therapy." (PMID 34873618, 2021).
tumor (6 papers, 2020 to 2025). "The effect of RPL21 expression on CRC tumor metastasis in vivo was assessed by preparing a CRC liver metastasis model." (PMID 37062845, 2023). "Then, we detected the protein expression of LAMP3 in 18 pairs of fresh human CRC tissues (T) and matched adjacent normal tissues (N), and observed higher expression of LAMP3 in tumor tissues, similar to the expression trends for RPL21." (PMID 37062845, 2023). "Taken together, our results suggest that the upregulation of RPL21 in CRC tissues contributes to tumor invasiveness and poor patient prognosis." (PMID 37062845, 2023). "Then, we investigated the transcriptional level of RPL21 using the Gene Expression Omnibus databases GSE83889 and GSE87211, and observed higher RPL21 expression in CRC tumor samples than in normal counterparts." (PMID 37062845, 2023). "In the present study, we discovered that RPL21 expression in CRC was positively correlated with tumor metastasis and poor patient prognosis." (PMID 37062845, 2023). "Our study provides a new perspective to investigate the tumor-promoting mechanism of RPL21 and may help develop novel therapeutic strategies against CRC." (PMID 37062845, 2023). "Then, tumoral RPL21 gene expression from tumor homogenates was evaluated by qPCR and western blot." (PMID 33014855, 2020). "Notably, RPL21 had higher expression in the invasive front than in the central tumor area." (PMID 37062845, 2023). "Moreover, RPL21 is markedly upregulated in metastatic 5-8F compared with nonmetastatic 6–10B nasopharyngeal carcinoma cell lines, which is associated with tumor metastasis." (PMID 37062845, 2023). "Functionally, RPL21 promoted the migration and invasion of CRC cells in vitro and tumor metastasis in vivo." (PMID 37062845, 2023). "Lastly, we analyzed the correlation between the scores of RPL21 and LAMP3 expression in tumor buds and observed a significant positive correlation." (PMID 37062845, 2023). "In the top 10 altered couples for these tumor types, 9 are identical: SNORA13/EBP41L4A-AS1, SNORA27/RPL21, SNORA31/TPT1, SNORA71E/SNHG11, SNORA72/RPL30, SNORD102/RPL21, SNORD12/ZFAS1, SNORD12B/ZFAS1, and SNORD12C/ZFAS1." (PMID 32046192, 2020). "The effects of RPL21 knockdown on PANC-1 and BxPC-3 cell proliferation in vivo were determined using BALB/c nude mice tumor model." (PMID 33014855, 2020). "Functional experiments confirmed that RPL21 could promote CRC cell migration and invasion in vitro and tumor metastasis in vivo." (PMID 37062845, 2023). "RPL21 was highly expressed in CRC, contributing to tumor invasiveness and poor patient prognosis." (PMID 37062845, 2023). "The prometastatic effect of RPL21 in CRC, as presented in this study, may be a coping strategy by which CRC cells escape the unfavorable tumor microenvironment." (PMID 37062845, 2023). "Therefore, we focused on RPL21 expression in tumor buds, an independent predictor of CRC metastasis, and observed that high RPL21 expression in tumor buds was positively correlated with high-grade tumor budding." (PMID 37062845, 2023).
bacterial infection (1 paper, 2021). "RPL21 is upregulated in murine platelet cells following Chlamydia pneumoniae infection, implicating it in immune response to bacterial infection." (PMID 34684597, 2021).
cardiovascular disease (1 paper, 2024). "RPL21, RPL26, and RPL10A are important components of the large 60S ribosomal subunit with functions involved in cell proliferation, differentiation, apoptosis, and DNA repair, which have been associated with metabolism and cardiovascular disease progression." (PMID 38503760, 2024).
infection (1 paper, 2015). The state of being infected such as from the introduction of a foreign agent such as serum, vaccine, antigenic substance or organism. "Genes, such as Serpina1a, Ttr, Fgg, Rpl21, and Alb, were uniquely affected by infection and diet." (PMID 26148065, 2015).
RPL21 also shares sentences with these, for which no sentence is quoted: alopecia (1 paper); Alzheimer disease (1); cervical intraepithelial neoplasia (1); colorectal cancer (1); Diabetes (1); hereditary hypotrichosis simplex (1); hypotrichosis (1); lymphoma (1); mastitis (1); neurological disease (1); osteosarcoma (1); ovarian carcinoma (1); Sepsis (1); squamous cell carcinoma (1); tauopathies (1); uterine cancer (1); uterine diseases (1).